TLR2 (toll like receptor 2)
Description:
Cooperates with LY96 to mediate the innate immune response to bacterial lipoproteins and other microbial cell wall components. Cooperates with TLR1 or TLR6 to mediate the innate immune response to bacterial lipoproteins or lipopeptides. Acts via MYD88 and TRAF6, leading to NF-kappa-B activation, cytokine secretion and the inflammatory response. May also activate immune cells and promote apoptosis in response to the lipid moiety of lipoproteins. Recognizes mycoplasmal macrophage-activating lipopeptide-2kD (MALP-2), soluble tuberculosis factor (STF), phenol-soluble modulin (PSM) and B.burgdorferi outer surface protein A lipoprotein (OspA-L) cooperatively with TLR6. Stimulation of monocytes in vitro with M.tuberculosis PstS1 induces p38 MAPK and ERK1/2 activation primarily via this receptor, but also partially via TLR4. MAPK activation in response to bacterial peptidoglycan also occurs via this receptor. Acts as a receptor for M.tuberculosis lipoproteins LprA, LprG, LpqH and PstS1, some lipoproteins are dependent on other coreceptors (TLR1, CD14 and/or CD36); the lipoproteins act as agonists to modulate antigen presenting cell functions in response to the pathogen. M.tuberculosis HSP70 (dnaK) but not HSP65 (groEL-2) acts via this protein to stimulate NF-kappa-B expression. Recognizes M.tuberculosis major T-antigen EsxA (ESAT-6) which inhibits downstream MYD88-dependent signaling (shown in mouse) (By similarity). Forms activation clusters composed of several receptors depending on the ligand, these clusters trigger signaling from the cell surface and subsequently are targeted to the Golgi in a lipid-raft dependent pathway. Forms the cluster TLR2:TLR6:CD14:CD36 in response to diacylated lipopeptides and TLR2:TLR1:CD14 in response to triacylated lipopeptides. Required for normal uptake of M.tuberculosis, a process that is inhibited by M.tuberculosis LppM (By similarity).
Synonyms: CD282; TIL4
Tractability: Small molecule: a drug acting on it is in phase 2 or 3 trials; a structure with a bound ligand is known; a high-quality ligand is known; it has a high-quality binding pocket; it belongs to a druggable protein family. Antibody: a drug acting on it is in phase 2 or 3 trials; its Gene Ontology location is reachable by antibodies, with high confidence; UniProt predicts a signal peptide or a membrane-spanning region; the Human Protein Atlas places it where antibodies can reach. PROTAC: UniProt records ubiquitination sites on it; its protein half-life has been measured; a small molecule that binds it is known.
Target class: Toll-like and Il-1 receptors; Membrane receptor
Gene: Protein-coding gene on chromosome 4 (153,684,050 to 153,708,537, forward strand). Ensembl gene ENSG00000137462.
Subcellular location: Membrane; Cytoplasmic vesicle, phagosome membrane; Membrane raft
Subcellular location (Human Protein Atlas): Plasma membrane; Cytosol; Nucleoplasm; Vesicles
Pathways (Reactome):
Immune System: Beta defensins; ER-Phagosome pathway; MyD88:MAL(TIRAP) cascade initiated on plasma membrane; Neutrophil degranulation; Regulation of TLR by endogenous ligand; Toll Like Receptor TLR1:TLR2 Cascade; Toll Like Receptor TLR6:TLR2 Cascade
Disease: IRAK4 deficiency (TLR2/4); Modulation by Mtb of host immune system; MyD88 deficiency (TLR2/4); RSV-host interactions; SARS-CoV-2 activates/modulates innate and adaptive immune responses
Gene Ontology:
Molecular function: amyloid-beta binding; identical protein binding; lipopolysaccharide binding; lipopolysaccharide immune receptor activity; pattern recognition receptor activity; peptidoglycan binding; protein binding; protein-containing complex binding; Toll-like receptor binding; transmembrane signaling receptor activity; triacyl lipopeptide binding; signaling receptor activity
Biological process: antibacterial innate immune response; cellular response to diacyl bacterial lipopeptide; cellular response to lipoteichoic acid; cellular response to triacyl bacterial lipopeptide; cellular response to type II interferon; defense response to Gram-positive bacterium; defense response to virus; detection of diacyl bacterial lipopeptide; detection of triacyl bacterial lipopeptide; positive regulation of canonical NF-kappaB signal transduction; positive regulation of cellular response to macrophage colony-stimulating factor stimulus; positive regulation of chemokine production; positive regulation of gene expression; positive regulation of inflammatory response; positive regulation of interleukin-6 production; positive regulation of interleukin-8 production; positive regulation of matrix metallopeptidase secretion; positive regulation of transcription by RNA polymerase II; positive regulation of Wnt signaling pathway; toll-like receptor 2 signaling pathway; toll-like receptor signaling pathway; toll-like receptor TLR1:TLR2 signaling pathway; toll-like receptor TLR6:TLR2 signaling pathway; cellular response to bacterial lipopeptide; inflammatory response; and 12 more
Cellular component: cell surface; cytoplasm; Golgi apparatus; membrane raft; plasma membrane; plasma membrane raft; receptor complex; Toll-like receptor 1-Toll-like receptor 2 protein complex; Toll-like receptor 2-Toll-like receptor 6 protein complex; membrane; secretory granule membrane; phagocytic vesicle membrane
Genetic constraint (gnomAD): Loss-of-function variants: 13 observed, 14.41 expected, observed/expected ratio (o/e) 0.9, 90% interval 0.59 to 1.43. The upper end of that interval is the gene's LOEUF score, 1.43, which puts it in group 5 of 6, group 1 being the genes least tolerant of losing a copy. Missense variants: 812 observed, 951.58 expected, observed/expected ratio (o/e) 0.85, 90% interval 0.81 to 0.9. Synonymous variants: 317 observed, 364.23 expected, observed/expected ratio (o/e) 0.87, 90% interval 0.79 to 0.95.
Homologues: Orthologues: chimpanzee TLR2 (99% identical), macaque TLR2 (96% identical), pig TLR2 (79% identical), dog TLR2 (77% identical), rabbit TLR2 (76% identical), guinea pig TLR2 (72% identical), rat Tlr2 (72% identical), mouse Tlr2 (71% identical), tropical clawed frog tlr2 (49% identical), tropical clawed frog tlr2 (46% identical), zebrafish tlr2 (41% identical). Paralogues in human: TLR6 (30% identical), TLR10 (29% identical), TLR1 (28% identical), TLR8 (23% identical), TLR7 (22% identical), TLR4 (22% identical), TLR3 (19% identical), TLR5 (19% identical), NRROS (15% identical), CD180 (15% identical), RXFP1 (14% identical), LRRC32 (14% identical), and 10 more.
Diseases named in the same sentence as TLR2 in open-access papers:
TLR2 is named in the same sentence as 786 diseases in open-access papers, as found by Europe PMC text mining. Sharing a sentence is not in itself a finding about the gene and the disease. The quoted sentences say what the papers report.
Sepsis (222 papers, 2006 to 2026). Sepsis is defined as life-threatening organ dysfunction caused by a dysregulated host response to infection. "Research indicates that TLR2, a Toll-like receptor that recognizes pathogen-associated molecular patterns (PAMPs), activates the NF-κB pathway in sepsis, promoting the release of inflammatory cytokines and exacerbating systemic inflammatory response." (PMID 41252417, 2025). "During sepsis, TLR2 and TLR4 recognize pathogen-associated molecular patterns (PAMPs) derived from invading microorganisms, such as lipopolysaccharide (LPS) from Gram-negative bacteria." (PMID 40386784, 2025). "Chronic L. sigmodontis infection has been found to improve sepsis outcomes caused by E. coli by reducing inflammation and enhancing bacterial clearance, and it also affects macrophage function through Wolbachia and TLR2 signaling." (PMID 40432048, 2025). "Other transcripts upregulated in CD5L− peritoneal cells, including Osm, Il18bp, Ripk1, Nub1, Tlr2, Stat1, Irf1, Nfkb1, Pik3r5, or their coding proteins, were already associated with sepsis severity." (PMID 38750020, 2024). "In the same sepsis mouse model, another group has recently demonstrated that TLR2-deficient mice have lower levels of IL-10 and reduced caspase-3 activation in the spleen." (PMID 37569837, 2023). "Rationale: Abdominal polymicrobial sepsis induces dramatic susceptibility to secondary bacterial pneumonia (i.e.)dependent on TLR2 signalling as suggested by the particular resistance of Tlr2−/− post-septic mice to secondary Pseudomonas aeruginosa pneumonia." (PMID 37311846, 2023). "The analysis showed that NOS3, SIRT1, HSP90AA1, MMP9, MMP2, PTPRC, and TLR2 were associated with multiple organ damage in sepsis." (PMID 36406124, 2022). "There was a significant association between TLR2 Arg753Gln polymorphisms and sepsis under the over-dominant model (p = 0.043)." (PMID 36142893, 2022). "In another study, genotype CC of rs3804100 (TLR2) was associated with a significantly increased risk of developing severe sepsis." (PMID 36611413, 2022). "The soluble form of biglycan initiates and perpetuates the inflammatory response by activating TLR2 and TLR4, and biglycan-deficient mice are less susceptible to death caused by TLR2- or TLR4-dependent sepsis." (PMID 32194548, 2020). "In AML patients TLR2 Arg753Gln gene polymorphism is associated with high susceptibility to sepsis and TLR4 (Asp299Gly and Thr399Ile) gene polymorphism is associated with high susceptibility for both pneumonia; and sepsis." (PMID 33247673, 2020). "The incidence of sepsis was associated with TLR2 Arg753Gln: AG genotypes, A allele and TLR4 Asp299Gly: CT genotype and C allele as compared to other genotypes and alleles." (PMID 33247673, 2020). "Our findings show that fEVs cause sepsis-like systemic inflammation, when introduced intraperitoneally, a process regulated by TLR2 and TLR4." (PMID 30131776, 2018). "Toll-like receptor 2 (TLR2) has been implicated in the orchestration of inflammation and sepsis but its role appears to vary for different pathogen species and clones." (PMID 27470911, 2016). "After removing these two studies from the overall analysis, the between-study heterogeneity decreased substantially and the association between the TLR2 Arg753Gln polymorphism and sepsis risk was still significant." (PMID 26616674, 2015). "We found significant associations between the TLR2 Arg753Gln polymorphism and sepsis risk in two genetic models (the allele comparison model and the dominant model)." (PMID 26616674, 2015). "Recently, a large number of studies have been conducted to explore the association between the TLR2 Arg753Gln polymorphism and sepsis risk." (PMID 26616674, 2015). "In this meta-analysis, we aimed to confirm the effect of the TLR2 Arg753Gln polymorphism on sepsis risk." (PMID 26616674, 2015). "TLR2, associated with deleterious systemic inflammation, cardiac dysfunction, and acute kidney injury, acts synergistically in sepsis." (PMID 26599367, 2015).
Sepsis (continued). "A total of 12 studies (11 records) with 898 cases and 1517 controls were examined to determine the association between the TLR2 Arg753Gln polymorphism and sepsis risk." (PMID 26616674, 2015). "Preventive treatment with mAbs targeting either TLR2 (T2.5) or TLR4 (1A6) caused a significant improvement in the survival rate during severe sepsis compared to the isotype control group, where 100% of the mice subjected to CLP succumbed within 24 hours." (PMID 26147469, 2015). "There was a significant association between the TLR2 Arg753Gln polymorphism and sepsis risk (for AA/GA vs. GG, OR 1.44, 95 % CI 1.02–2.03, P = 0.04)." (PMID 26616674, 2015). "The odds ratios with their corresponding 95 % confidence intervals were used to assess the association between the TLR2 Arg753Gln polymorphism and sepsis risk." (PMID 26616674, 2015). "More studies in Asian populations are needed to estimate the effect of the TLR2 Arg753Gln polymorphism on sepsis risk." (PMID 26616674, 2015). "In our meta-analysis, we pooled all available data related to potential links between the TLR2 Arg753Gln polymorphism and sepsis risk." (PMID 26616674, 2015). "We noted that the TLR2 Arg753Gln polymorphism was also significantly associated with sepsis risk in adult, European, sepsis, and critically ill patient subgroups." (PMID 26616674, 2015). "Pre-treatment with anti-TLR2 or anti-TLR4 mAb alone showed significant protection from sepsis-associated death." (PMID 26147469, 2015). "The association between the TLR2 Arg753Gln polymorphism and sepsis risk changed little (for A vs. G, OR 1.74, 95 % CI 1.15–2.63, P = 0.009)." (PMID 26616674, 2015). "There were significant associations between the TLR2 Arg753Gln polymorphism and sepsis risk in overall analyses under two genetic models (the allele comparison and the dominant model)." (PMID 26616674, 2015). "Our present meta-analysis supports a direct effect of the TLR2 Arg753Gln polymorphism on sepsis risk, especially in Europeans." (PMID 26616674, 2015). "In order to corroborate the effect of the ENV TMD on TLR2 activation in vivo we utilized a murine model for acute sepsis caused by hyper-activation of TLR2." (PMID 25121610, 2014). "In a recent sepsis study we were able to show in a late phase of human sepsis (day 3) an association of TLR2 and CD14 expression on monocytes with the cytokine hyporesponsiveness." (PMID 23414215, 2013). "Nevertheless, previous reports have shown associations of the rs3804099 polymorphism in the TLR2 gene with sepsis in preterm infants." (PMID 21931695, 2011). "Previous studies have shown that TLR2−/− mice have an increased susceptibility to S. aureus, and have higher bacterial loads during S. aureus sepsis." (PMID 20657826, 2010). "Our studies identified that another tagging SNP in TLR2 gene (19216T/C) was associated with cytokine production and seemed to confer an increased risk of sepsis and MODS after trauma." (PMID 21274447, 2010). "In contrast to downregulation of TLR gene expression after LPS exposure in cell culture, sepsis in mice and humans sepsis causes an upregulation of TLR2, TLR4 and CD14 expression on blood monocytes." (PMID 19371402, 2009). "To determine the role of elevated myocardial TLR2 level in aging-related exacerbation of myocardial inflammatory activity and cardiac dysfunction in sepsis, we determined myocardial inflammatory response to TLR2 agonist and associated cardiac functional change in young adult and old WT mice." (PMID 38094127, 2023). "Meanwhile, one of the most important polymorphisms of TLR2 is Arg753Gln; the presence of this SNP was found to impair the signaling pathway of this key receptor, thus suggesting increased susceptibility to infections and sepsis." (PMID 36142893, 2022). "Indeed, it has been demonstrated that lipoprotein detection by TLR2 contributes to the development of neonatal sepsis caused by Group B Streptococcus." (PMID 34527000, 2021).
Sepsis (continued). "Similarly, in a study on sepsis patients, TLR2 was upregulated in sepsis; however, mortality was associated with TLR2 downregulation." (PMID 33256638, 2020). "This could be clinically important as excess TLR2 expression is associated with morbidities seen more commonly in DS, such as gram-positive infections, autoimmunity, and poorer outcomes in sepsis." (PMID 31611734, 2019). "In addition, TLR4 knockout mice are resistant to Gram-negative bacteria-induced septic shock, and TLR2-deficient mice have increased survival rates compared to wild type mice in a polymicrobial sepsis model." (PMID 28769820, 2017). "Moreover, the GA heterozygosity within TLR2 2258 polymorphism was shown to be involved in tuberculosis among Turkish children, as well as Candida sepsis in German adult patients." (PMID 28118851, 2017). "Since E. gallinarum could induce cellular activation through a TLR2/6-dependent pathway and since this receptor plays a pivotal role in mortality during severe sepsis, we challenged TLR2-deficient mice with E. gallinarum." (PMID 29375557, 2017). "All of these findings are in agreement with our results, indicating that the TLR2 Arg753Gln polymorphism may affect the risk of sepsis." (PMID 26616674, 2015). "In addition, subgroup analyses showed significant associations between the TLR2 Arg753Gln polymorphism and sepsis risk in the adult group." (PMID 26616674, 2015). "Similarly, transfer of macrophages from L. sigmodontis-infected mice improved sepsis outcome more efficiently, than macrophages derived from naïve wild type or L. sigmodontis-infected TLR2-deficient mice." (PMID 25611587, 2015). "TLR2 or TLR4-deficient mice are more resistant to polymicrobial sepsis." (PMID 26147469, 2015). "In addition, subgroup analyses based on age group, ethnicity, sepsis type, and source of control also showed a significant effect of the TLR2 Arg753Gln polymorphism on sepsis risk." (PMID 26616674, 2015). "Thus, we performed a meta-analysis to further investigate the effect of the TLR2 Arg753Gln polymorphism on sepsis risk." (PMID 26616674, 2015). "The TLR2 Arg753Gln polymorphism might be used as a relevant risk estimate for the development of sepsis." (PMID 26616674, 2015). "We demonstrate that LP are the most potent non-LPS pro-inflammatory toxins of the bacterial cell walls, signalling via Toll-like receptor-2, not only in vitro, but also when inoculated into mice: A synthetic LP caused sepsis-related pathological symptoms in a dose-response manner." (PMID 26390973, 2015). "Also, the TLR2 Arg753Gln polymorphism increased sepsis risk in the European and critically ill patient subgroups, respectively." (PMID 26616674, 2015). "The evidence suggested that the TLR2 Arg753Gln polymorphism could increase sepsis risk, especially in European populations, which may help us identify high-risk patients." (PMID 26616674, 2015). "The most commonly discussed polymorphisms in TLR2, the R677W and R753Q, have been shown to be associated, amongst other diseases, with leprosy, tuberculosis, staphylococcal infections, coronary restenosis and sepsis." (PMID 21931695, 2011). "Beside innate immune response, the TLR2 induced cytokine response might also be involved in the physiologic endocrine response to sepsis, since TLR2 deficient mice have an impaired cytokine mediated corticosteroid adrenal stress response." (PMID 19371402, 2009). "We hypothesize that monocyte hyporesponsiveness in human sepsis is associated with a downregulation of the pattern recognition receptors Toll-like receptor (TLR)-2 and TLR4." (PMID 19371402, 2009). "Death due to sepsis is associated with TLR2 and CD14 downregulation." (PMID 19371402, 2009). "In the present study we aimed to characterize the expression and function of TLRs in sepsis caused by B. pseudomallei and found that, although both TLR2 and TLR4 contribute to cellular responsiveness to B. pseudomallei in vitro, only TLR2 impacts on the immune response of the intact host in vivo." (PMID 17676990, 2007).